LAMC1 (laminin subunit gamma 1)
Description:
Binding to cells via a high affinity receptor, laminin is thought to mediate the attachment, migration and organization of cells into tissues during embryonic development by interacting with other extracellular matrix components. As a subunit of laminin-1 (also known as laminin-111 or EHS laminin), it is involved in the stimulation of agrin-induced receptor clustering through a MuSK-independent pathway.
Synonyms: LAMB2
Tractability: Antibody: its Gene Ontology location is reachable by antibodies, with high confidence; UniProt places it where antibodies can reach, with medium confidence; UniProt predicts a signal peptide or a membrane-spanning region. PROTAC: ubiquitination databases record sites on it; its protein half-life has been measured. Other modalities: an approved drug acts on it.
Gene: Protein-coding gene on chromosome 1 (183,023,420 to 183,145,592, forward strand). Ensembl gene ENSG00000135862.
Subcellular location: Secreted, extracellular space, extracellular matrix, basement membrane
Subcellular location (Human Protein Atlas): Endoplasmic reticulum; Plasma membrane; Predicted to be secreted
Pathways (Reactome):
Extracellular matrix organization: Degradation of the extracellular matrix; ECM proteoglycans; Formation of the dystrophin-glycoprotein complex (DGC); Laminin interactions; Non-integrin membrane-ECM interactions
Developmental Biology: Developmental Lineage of Pancreatic Ductal Cells; EGR2 and SOX10-mediated initiation of Schwann cell myelination; L1CAM interactions
Metabolism of proteins: Post-translational protein phosphorylation; Regulation of Insulin-like Growth Factor (IGF) transport and uptake by Insulin-like Growth Factor Binding Proteins (IGFBPs)
Disease: Attachment of bacteria to epithelial cells
Signal Transduction: MET activates PTK2 signaling
Gene Ontology:
Molecular function: extracellular matrix structural constituent; extracellular matrix constituent conferring elasticity; receptor ligand activity
Biological process: cell adhesion; cell migration; extracellular matrix disassembly; hemidesmosome assembly; protein-containing complex assembly; substrate adhesion-dependent cell spreading; endoderm development; maintenance of blood-brain barrier; positive regulation of cell adhesion; positive regulation of epithelial cell proliferation; positive regulation of integrin-mediated signaling pathway; positive regulation of muscle cell differentiation; positive regulation of skeletal muscle acetylcholine-gated channel clustering; regulation of basement membrane organization; regulation of cell adhesion; regulation of cell migration; regulation of embryonic development; signal transduction; tissue development
Cellular component: basement membrane; extracellular exosome; extracellular matrix; laminin-10 complex; endoplasmic reticulum lumen; extracellular region; laminin-1 complex; laminin-11 complex; laminin-2 complex; laminin-3 complex; laminin-4 complex; laminin-6 complex; laminin-7 complex; laminin-8 complex; laminin-9 complex; protein complex involved in cell-matrix adhesion
Genetic constraint (gnomAD): Loss-of-function variants: 32 observed, 162.91 expected, observed/expected ratio (o/e) 0.2, 90% interval 0.15 to 0.26. The upper end of that interval is the gene's LOEUF score, 0.26, which puts it in group 1 of 6, group 1 being the genes least tolerant of losing a copy. Missense variants: 1,709 observed, 2,008.7 expected, observed/expected ratio (o/e) 0.85, 90% interval 0.82 to 0.88. Synonymous variants: 688 observed, 730.01 expected, observed/expected ratio (o/e) 0.94, 90% interval 0.88 to 1.
Homologues: Orthologues: chimpanzee LAMC1 (99% identical), macaque LAMC1 (99% identical), pig LAMC1 (96% identical), dog LAMC1 (95% identical), mouse Lamc1 (93% identical), rat Lamc1 (92% identical), guinea pig LAMC1 (90% identical), tropical clawed frog lamc1 (75% identical), rabbit LAMC1 (52% identical), zebrafish lamc2 (14% identical). Paralogues in human: LAMC3 (43% identical), LAMA5 (27% identical), LAMA3 (25% identical), LAMA2 (24% identical), LAMA1 (24% identical), LAMB2 (24% identical), LAMB1 (23% identical), HSPG2 (23% identical), LAMB4 (22% identical), LAMC2 (21% identical), USH2A (19% identical), LAMB3 (14% identical), and 15 more.
Diseases named in the same sentence as LAMC1 in open-access papers:
LAMC1 is named in the same sentence as 102 diseases in open-access papers, as found by Europe PMC text mining. Sharing a sentence is not in itself a finding about the gene and the disease. The quoted sentences say what the papers report.
gastric cancer (11 papers, 2016 to 2025). A primary or metastatic malignant neoplasm involving the stomach. "Aberrant expression of LAMC1 has been associated with various biological and clinical characteristics in several cancers, including gastric cancer, hepatocellular carcinoma, renal cell carcinoma, colorectal cancer, and lung cancer." (PMID 41093273, 2025). "Previous reports have suggested that high expression of LAMC1 is associated with a poor prognosis of certain tumors, such as esophageal squamous cell carcinoma, endometrial cancer, gastric cancer, KIRP and hepatocellular carcinoma." (PMID 38678297, 2024). "Above results demonstrated that gastric cancer with high LAMC1 expression had high risk of peritoneal metastasis." (PMID 35541892, 2022). "Previous studies have found that LAMC1 plays a role in the progression of gastric cancer, endometrial cancer, prostate cancer, breast cancer, and other tumors." (PMID 37138286, 2023). "We also constructed an in vitro coculture model to simulate the interaction between tumor cells and preadipocytes in peritoneal microenvironment evaluating the effect of gastric cancer cell CM with LAMC1 knockout on preadipocytes differentiation." (PMID 35541892, 2022). "Our study showed LAMC1-mediated interaction between preadipocytes and gastric cancer cells remodeled tumor cell metabolic programming." (PMID 35541892, 2022). "The Oil Red O staining showed that lipid droplet content increased when gastric cancer cell cocultured with LAMC1-induced 3T3-L1 CM." (PMID 35541892, 2022). "To further explore the role of LAMC1, we collected 90 specimens of gastric cancer for immunohistochemistry and LAMC1 expression was high in specimens whose average optical density is higher than the median." (PMID 35541892, 2022). "In our study, we found that gastric cancer cells secreted LAMC1 to obtain mobility ability by autocrine mode and promote preadipocyte maturation in a paracrine manner." (PMID 35541892, 2022). "All above results suggested that LAMC1-induced 3T3-L1 CM remodeled gastric cancer cell metabolic programming." (PMID 35541892, 2022). "Totally, palmitic acid/p-STAT3/miR-193a-3p/LAMC1 regulation circuitry was favorable for gastric cancer peritoneal metastasis." (PMID 35541892, 2022). "Our results showed that high LAMC1 expression was closely associated with T stage, TNM stage and peritoneal metastasis of gastric cancer." (PMID 35541892, 2022). "In our study, when LAMC1 wasn't knockdown in gastric cancer and LAMC1 expression was at a high level, the migration and invasion ability of gastric cancer was significantly upregulated at the primary site." (PMID 35541892, 2022). "At present, our results show that LAMC1 is highly expressed in gastric cancer and mainly secreted by gastric cancer cell which is associated with poor prognosis." (PMID 35541892, 2022). "Transwell assay results showed gastric cancer cells with stable LAMC1 expression acquired enhancive cell migratory and invasive ability than LAMC1 knockout groups." (PMID 35541892, 2022). "Collectively, our study deciphered the molecular mechanisms that p-STAT3 / miR-193a-3p / LAMC1 axis was an essential signaling pathway of gastric cancer peritoneal metastasis." (PMID 35541892, 2022). "Our research demonstrated that the elevated LAMC1 expression was related to poor prognosis of patients with gastric cancer which was consistent with many studies that LAMC1 promoted malignant tumor progression." (PMID 35541892, 2022). "We used western blots and ELISA to examine the expression of LAMC1 and the results showed that LAMC1 was up-regulated in cell lines and the conditioned medium of gastric cancer in protein level." (PMID 35541892, 2022). "Further mechanistic studies revealed that gastric cancer cells orchestrate palmitic acid/p-STAT3/miR-193a-3p/LAMC1 axis to support more LAMC1 secretion, which further favors preadipocyte maturation to consolidate pre-metastatic niche." (PMID 35541892, 2022).
gastric cancer (continued). "FFAs-activated p-STAT3/miR-193a-3p/LAMC1 axis played an important feedback regulation role in the reciprocal interaction between gastric cancer cells and preadipocytes which directly contributed to gastric cancer peritoneal metastasis." (PMID 35541892, 2022). "In our study, p-STAT3/miR-193a-3p/LAMC1 signaling axis is corroborated to have a powerful effect in metastasis of gastric cancer to adipocyte-rich peritoneum which provides a new sight for targeted therapy." (PMID 35541892, 2022). "To further determine how adipocyte-derived adipokines, inflammatory cytokines, FFAs and lipid droplets functioned on gastric cancer cells, we used the adipocytes CM induced by LAMC1 to reverse co-culture with gastric cancer cell lines." (PMID 35541892, 2022). "In conclusion, our results illustrated that palmitic acid/p-STAT3/miR-193a-3p/LAMC1 pathway promotes preadipocyte differentiation, pre-metastatic niche formation and gastric cancer cell colonization to peritoneum." (PMID 35541892, 2022). "Cell scratch test confirmed that gastric cancer with LAMC1 knockout had lower wound healing ability." (PMID 35541892, 2022). "In vitro co-culture experiments have shown that gastric cancer cells secrete LAMC1 protein to enhance mobility by autocrine way and adipogenesis in a paracrine manner." (PMID 35541892, 2022). "LAMC1 is also secreted by gastric cancers, and it accumulated in the pre-metastatic peritoneal microenvironment, where it induced preadipocyte maturation (i.e., differentiation) and altered their metabolism and function, resulting in the release of free fatty acids." (PMID 37350937, 2023). "However, how adipocyte-derived FFAs affecting LAMC1 and metabolic regulation promotes gastric cancer progression is still unclear." (PMID 35541892, 2022). "Laminin gamma 1 (LAMC1) is highly expressed in cancer cells of peritoneal metastatic sites, however, the mechanism of LAMC1-metiated gastric cancer metastases to adipose tissue-rich peritoneum remains unclear." (PMID 35541892, 2022). "Furthermore, according to single cell sequencing data of gastric cancer, LAMC1 was mainly from fibroblasts and cancer cells." (PMID 35541892, 2022). "The overexpression of LAMC1 is related to tumor progression and poor prognosis in cancers such as endometrial carcinoma, hepatocellular carcinoma, gastric cancer and meningioma, highlighting the significance of molecular targeting LAMC1 in cancer treatment." (PMID 36188228, 2022). "LAMC1 was a prediction marker gene for gastric cancer peritoneal metastasis and it might be a potential therapeutic target for gastric cancer progression." (PMID 35541892, 2022). "Additionally, the higher the concentration of LAMC1 that induced 3T3-L1, the richer the content of lipid droplets in gastric cancer cells." (PMID 35541892, 2022). "Our previous mass spectrometry results showed that compared with the primary tumor, LAMC1 was highly expressed in gastric cancer peritoneal metastases and GO enrichment analysis revealed that LAMC1 was involved in ECM organization, disassembly and substrate adhesion-dependent cell spreading." (PMID 35541892, 2022). "Gastric cancer cells secreted LAMC1 in an autocrine manner to detached from the primary site and promoted preadipocytes mature, rupture and release of free fatty acids (FFAs) in the peritoneal microenvironment to form pre-metastatic niche by the paracrine pathway." (PMID 35541892, 2022). "Due to technical limitations, we couldn't construct the LAMC1 overexpression plasmid, so it was our limitations that only LAMC1 knockout cell lines were used to compare and judge the change of invasion and migration ability of gastric cancer cells." (PMID 35541892, 2022). "Therefore, we postulate that gastric cancer cells can rewire their biology to secrete more LAMC1 to act on preadipocytes, promote lipid formation and peritoneal metastasis, and yet the mechanisms of interaction have not been fully elucidated." (PMID 35541892, 2022).
gastric cancer (continued). "Although ITGB1 and LAMC1 were both tightly related to the prognosis of gastric cancer, it was suggested that LAMC1 might be involved in a more complex molecular mechanism, rather than being directly regulated by FTO." (PMID 34277426, 2021). "Given the biological and physical functions of LAMC1, we speculate that gastric cancer cells secrete LAMC1 to promote their abscission from the primary site and promote preadipocyte maturation to form pre-metastatic niche formation in peritoneal microenvironment." (PMID 35541892, 2022). "Of these fatty acids, palmitic acid regulated LAMC1 in a posttranslational manner and promoted PMN formation and gastric cancer cell colonization of the peritoneum." (PMID 37350937, 2023). "Our results demonstrated that gastric cancer cell with STAT3 knockout inhibited LAMC1 expression on protein levels significantly and STAT3 didn't affect LAMC1 mRNA expression." (PMID 35541892, 2022). "We further mimicked the primary foci of gastric cancer using subcutaneous tumorigenesis model of nude mice to explore our results in vivo animal assay, and found that AGS cells with low LAMC1 expression developed smaller tumor size and body weight." (PMID 35541892, 2022). "Expression of adhesion-related molecules, such as fibronectin 1 (FN1) and laminin gamma 1 (LAMC1), were increased in mesothelial cells after internalization of TEX from gastric cancer cell line and malignant pleural effusion." (PMID 27487135, 2016). "Our results also disclose that there is a negative correlation between palmitic acid and LAMC1 with miR-193a-3p in gastric cancer cells and LAMC1 is the target of miR-193a-3p regulated by p-STAT3." (PMID 35541892, 2022).
breast carcinoma (9 papers, 2013 to 2025). "The increased levels of both SNHG6 and LAMC1 are associated with poor prognosis in breast cancer." (PMID 37735423, 2023). "It has been proven that LAMC1 rarely methylated in breast cancer but our result illustrated the role of LAMC1 methylation in GC outcome, which suggests the prognostic significance of LAMC1 as well." (PMID 38549047, 2024). "SNHG6 promoted EMT and migration in breast cancer cells by sequestering miR-543 and hence elevating the expression of LAMC1, which is a target of miR-543." (PMID 37735423, 2023). "miR-543 sponging by SNHG6 leads to downstream expression of LAMC1 in breast cancer, while in glioma cells LMO3 gene is activated by binding of SNHG6 to miR-543." (PMID 37735423, 2023). "Although LAMC1 has multiple effects on biological activities, including cell adhesion, proliferation, migration, and differentiation, this study at least demonstrated that miR-205-5p inhibits breast cancer growth partly by targeting LAMC1." (PMID 31752366, 2019).
hepatocellular carcinoma (9 papers, 2019 to 2025). A malignant tumor that arises from hepatocytes. "Many previous studies have shown that high LAMC1 expression promotes tumor progression and can be used as a prognostic biomarker in many cancers, such as hepatocellular carcinoma, colorectal cancer and endometrial cancer." (PMID 34218518, 2021). "Of note, overexpression of LAMC1 increases the tumor cell invasion and migration and predicts the poor prognosis in hepatocellular carcinoma." (PMID 31884422, 2019). "Previous studies have shown that LAMC1 is regulated by SP1 in hepatocellular carcinoma." (PMID 34218518, 2021). "LAMC1 can also promote the Warburg effect by upregulating PKM2 in hepatocellular carcinoma." (PMID 34218518, 2021). "In hepatocellular carcinoma (HCC), LAMC1 competes for miR-124 binding and acts as a trans-regulator to induce the expression of CD151." (PMID 35511773, 2022). "However, in hepatocellular carcinoma, ASMTL-AS1 upregulation activates the YAP signaling pathway through the ASMTL-AS1/miR-1343-3p/LAMC1 axis, which results in a recurrence of the cancer or its metastasis." (PMID 39028420, 2024).
colorectal cancer (7 papers, 2018 to 2025). A primary or metastatic malignant neoplasm that affects the colon or rectum. "rs6695837, localized at 2kb upstream of the LAMC1 gene, affected the LAMC1 promoter activity and contributed to colorectal cancer susceptibility." (PMID 29844862, 2018). "The polymorphisms of LAMC1 gene have been reported to be associated with colorectal cancer, premature ovarian failure and Mayer-Rokitansky-Kuster-Hauser syndrome (MRKHS)." (PMID 32635941, 2020). "Computational analyses of laminin proteins have shown their prognostic ability in colorectal cancer progression, placing higher weights for LAMC1 compared to other constituents of the family." (PMID 40775447, 2025). "We find a similar pattern for colorectal cancer and ENST00000466964.1, an isoform of LAMC1 (six total isoforms), a gene that regulates cell adhesion, differentiation, migration, and signaling, and lies at a pleiotropic locus for CRC, PRCA, and obesity risk." (PMID 40775447, 2025). "We then assessed the role of LAMC1 and LAMB1 in H-1PV cellular uptake in two other cancer cell lines, namely HCT116 (colorectal carcinoma) and A549 (lung adenocarcinoma)." (PMID 34158478, 2021). "Surprisingly, there were several other pairs containing other than LAMA4, LAMC1, and LAMC2 genes with similar prognostic power in colorectal cancer." (PMID 29504916, 2018).
endometrial cancer (7 papers, 2021 to 2024). Primary or metastatic malignant neoplasm involving the endometrium (mucous membrane that lines the endometrial cavity). "LAMC1 gene, encoding laminin subunit gamma 1 (LAMC1) protein, has been demonstrated as a potent biomarker for aggressive endometrial cancer." (PMID 35585515, 2022). "A study showed that the overexpression of LAMC1 in endometrial carcinoma was related to aggressive histological types and LN metastasis; and LAMC1 knockdown suppressed cell motile and invasive properties in endometrial cancer cells." (PMID 34268116, 2021). "LAMC1 has recently been found to be overexpressed in endometrial cancer and is reported to be a potent biomarker for identifying endometrial cancer patients needing aggressive adjuvant therapy." (PMID 34771544, 2021).
lung carcinoma (7 papers, 2019 to 2025). "Except the EGFR, the long non-coding RNA H19 causes the progression and metastasis of lung cancer, and the LAMC1 SNP rs3768617 could also increase the risk of lung cancer." (PMID 36011604, 2022). "We highlight several isoTWAS associations that demonstrate GWAS colocalization at the isoform level but not at the gene level, including CLPTM1L (lung cancer), LAMC1 (colorectal), and BABAM1 (breast)." (PMID 40775447, 2025). "We speculate that hyperactivation of NRF2 in LUAD may lead to over-expression of LAMC1 that ultimately enhances the tumor cell invasion, migration, and metastasis and inhibition of NRF2 pathway is a promising approach for the lung cancer therapy." (PMID 31884422, 2019).